GALNT1 (polypeptide N-acetylgalactosaminyltransferase 1)
Diseases named in the same sentence as GALNT1 in open-access papers (continued):
Sharing a sentence is not in itself a finding about the gene and the disease.
ischemia (1 paper, 2024). A hypoperfusion of the BLOOD through an organ or tissue caused by a PATHOLOGIC CONSTRICTION or obstruction of its BLOOD VESSELS, or an absence of BLOOD CIRCULATION. "Validated targets of miR-129-5p are CAMTA1 (calmodulin-binding transcription factor), indicating a role of calcium under this condition, SOX4 (regulation of Wnt pathway), GALNT1 (modifying glycan structures), EIF2C3 and HMGB1, which has been shown to protect against ischemia/reperfusion injury." (PMID 39201485, 2024).
neuroblastoma (1 paper, 2016). Neuroblastoma (NB) is the most common solid, extracranial childhood tumor. "GALNT13, like GALNT1, is highly expressed in all neuroblastoma (NB) cells, but not in glioblastoma cells." (PMID 27322213, 2016).
osteosarcoma (1 paper, 2021). A usually aggressive malignant bone-forming mesenchymal neoplasm, predominantly affecting adolescents and young adults. "Moreover, both CLTC and SEPT11 were found to have consistently high expression in all osteosarcoma cells when compared to those in the osteoblast cells; conversely, the other two genes (GALNT1 and TMEM2) were not." (PMID 34185412, 2021).
schizophrenia (1 paper, 2023). A major psychotic disorder characterized by abnormalities in the perception or expression of reality. "GALNT1 catalyzes glycosylation of target proteins, and aberrant glycosylation of i.e. the GABAA receptor is a pathological hallmark in postmortem brains of patients suffering from schizophrenia." (PMID 36449109, 2023).
urothelial carcinoma (1 paper, 2023). A malignant neoplasm derived from the transitional epithelium of the urinary tract (urinary bladder, ureter, urethra, or renal pelvis). "Thus, to identify GALNTs that contribute to the urothelial carcinoma invasion, we measured GALNT1 to 14 isoforms expressions were examined using real-time RT-PCR." (PMID 38269087, 2023).
tumor (17 papers, 2014 to 2025). "Early studies reported that GALNT1 is highly expressed in a variety of tumors, promotes tumor growth and metastasis, and is associated with poor prognosis." (PMID 35334492, 2022). "Collectively, the initiation of O-glycosylation is associated with the relocation of GALNT1 to the ER during tumor progression and metastasis." (PMID 36439876, 2022). "Gm56415, also known as polypeptide N-acetylgalactosaminyltransferase 1 (GALNT1), is abnormally expressed in multiple cancers and affects tumor progression by initiating GalNAc-type O-glycosylation of various proteins." (PMID 39502510, 2024). "Subcutaneous tumor in vivo experiment was performed to investigate the function of GALNT1 in driving tumorigenesis." (PMID 36439876, 2022). "Compared to the NC group, the shGALNT1 group had a much smaller mean tumor volume and tumor weight, manifesting that targeted knockdown of GALNT1 expression effectively inhibited tumor proliferation in vivo." (PMID 36439876, 2022). "This study provides insights into the pathophysiological role of GALNT1 and the significance of abnormal O-glycosylation in GC tumor progression." (PMID 36439876, 2022). "The results further confirm that GALNT1 expression level is significantly increased in HCC tumors, p < 0.01, with 75% of the HCC patients exhibiting higher GALNT1 expression levels compared with the adjacent non-tumor tissues." (PMID 25730904, 2015). "Analysis of TCGA database by applying UALCAN, we examined GALNT1 expression in relation to several clinicopathological parameters in patients with GC, including tumor grade (grade 1, 2, 3), tumor stage (stages I, II, III, and IV), and lymph node stage (N0 1, 2, and 3)." (PMID 36439876, 2022). "Furthermore, we investigated the primary role of GALNT1 in CD44 modified O-glycans in GC cells using VVA lectins, which recognize tumor-associated Tn antigens." (PMID 36439876, 2022). "Expressing an ER-targeted GALNT1 in this tumor model strongly accelerates tumor growth." (PMID 30889231, 2019). "LGALS1, B4GALT6, and GALNT11 were upregulated and MGAT5, MAN1A1, MANBA, LUM, GALNT1 and 7, HAPLN3, and ST6GALNAC5 were downregulated in Fra-2 cl 1 select primary tumours, while MGAT4A was upregulated." (PMID 34693476, 2022). "The results revealed that GALNT1 and VVA were mainly expressed in the cytoplasm of GC cells and were considerably greater in primary tumor tissues than in neighboring normal tissues." (PMID 36439876, 2022). "Here, we showed that GALNT1 expression was increased in metastatic CRC cell lines and tumor tissues." (PMID 29915311, 2018). "Overexpression of GALNT1 enhances HCC cell malignant phenotypes but knockdown of GALNT1 suppresses HCC cell migration and invasion, and inhibits tumor metastasis in NOD/SCID mouse model." (PMID 25730904, 2015). "Notably, when GalNAc-T1 (GALNT1) is mislocalized from the Golgi to ER, consequential increase in O-glycosylation activates the matrix metalloproteinase MMP14 to promote tumor spread." (PMID 34957124, 2021). "The results reveal that GALNT1 expression level is often increased in HCC tumors, p < 0.05, with 60% of the HCC patients exhibiting increased GALNT1 expression levels in the tumors compared with the adjacent non-tumor tissues." (PMID 25730904, 2015). "Among the GTs highlighted in this process GALNT1, GALNT2 and GALNT3, members of the UDP-N-α-D galactosamine:polypeptide N-acetylgalactosaminyltransferases (GALNT) family, were described to be involved in different biological processes, including tumor progression, proliferation, and migration." (PMID 40096084, 2025). "Immunohistochemical staining of GALNT1 in 16 paired HCC tissues from the NTUH was performed and the staining intensity of tumor (T) and the adjacent non-tumor (N) tissues was scored from 0, +1, +2, and +3 for none, low, moderate, and high staining." (PMID 25730904, 2015).
cancer (13 papers, 2014 to 2024). A tumor composed of atypical neoplastic, often pleomorphic cells that invade other tissues. "Some studies had shown that the abnormal mutation of the glycosylation related gene GALNT1 would lead to the occurrence and progression of a variety of cancers, including BLCA." (PMID 37818187, 2023). "By contrast, GalNT1 can exhibit a mucin-independent function in cancer and be implicated in other pathways, such as EGFR signaling, by increasing EGFR degradation via decreasing of EGFR O-glycosylation." (PMID 30038662, 2018). "We found that the cancer cells, along with some other cells such as immune and stromal cells, were the main sources accounting for the observed GALNT1 expression in bulk tumors." (PMID 37444599, 2023). "In the TCGA pan-cancer database, increased GALNT1 expression was frequently observed in various cancers." (PMID 36439876, 2022). "Aberrantly expressed O-glycans have been reported in many cancers; however, the roles of GALNT1 in cancers remain largely unclear." (PMID 25730904, 2015). "LASS2 and GALNT1 were only present in samples from cancer group, meanwhile ARHGEF39 (in the array named Chromosome 9 open reading frame 100 (C9orf100)) and FOXO3 were absent in cancer group and could be detected in control group." (PMID 24458310, 2014). "Analysis among the downregulated genes revealed a direct interaction within GALNT1, C1GALT1C1 and MUC1, a protein that carries the Tn antigen, which is present in most of the cancers, including uterine cervical cancer cells." (PMID 30038662, 2018). "Of the genes expressed, cancer exosomes consistently contained GALNT1 and LASS2 transcripts while lacking FOXO3 and ARHGEF39 expression, with the opposite being true for the healthy samples." (PMID 33803085, 2021). "LASS2 and GALNT1 were present in cancer patients, while ARHGEF39 and FOXO3 were found only in non-cancer urinary vesicles." (PMID 24458310, 2014).
infection (1 paper, 2024). The state of being infected such as from the introduction of a foreign agent such as serum, vaccine, antigenic substance or organism. "AdV-5 replicated well in all O-glycosylation mutant cell lines on day 6 post-infection, though an initial delay in intracellular DNA synthesis was seen in C1GALT1C1 KO and GALNT1 KO on day 1 post-infection." (PMID 38757972, 2024).
GALNT1 also shares sentences with these, for which no sentence is quoted: Barrett esophagus (1 paper); bladder tumor (1); COVID-19 (1); esophageal cancer (1); glioblastoma (1); oral squamous cell carcinoma (1); prostate carcinoma (1); pulmonary valve stenosis (1); Sjögren’s Syndrome (1); Stroke (1); triple-negative breast carcinoma (1).